PIEZO1 (piezo type mechanosensitive ion channel component 1 (Er blood group))
Diseases named in the same sentence as PIEZO1 in open-access papers (continued):
Sharing a sentence is not in itself a finding about the gene and the disease.
osteoporosis (continued). "Importantly, we found that antibody-based blockade of Lcn2 reversed osteoporosis and marrow adiposity in Piezo1-deficient mice, suggesting that pharmacological/genetic inhibition of BMMSC-secreted Lcn2 may represent a promising pharmacotherapy for mechanical unloading-induced bone diseases." (PMID 41145414, 2025). "Clinical studies have also found that Piezo1 expression is generally downregulated in osteoporosis patients, suggesting its key role in bone metabolic homeostasis." (PMID 41195420, 2025). "Mice with a specific Piezo1 invalidation in BMMSCs exhibit osteoporosis and marrow adiposity, together with resistance to the beneficial effects of exercise on bone health." (PMID 41145414, 2025). "Studies have shown that Piezo1 knockout mice exhibit skeletal deformities during development and develop osteoporosis in adulthood, highlighting the importance of Piezo1 in osteocyte function and bone health." (PMID 41195420, 2025). "In line with our findings, emerging clinical evidence suggests that the Piezo1-Klf2-Ccl2-Lcn2 axis is altered in patients with osteoporosis." (PMID 41145414, 2025). "The specific Piezo1 agonist Yoda1 enhances osteoblast mineralization ability in vitro and significantly increases bone density in mouse models, partially reversing osteoporosis." (PMID 41195420, 2025). "Targeted deletion of Piezo1 in osteoblasts resulted in severe osteoporosis and spontaneous fractures, highlighting Piezo1’s function in growth plate chondrocytes." (PMID 39170742, 2024). "PIEZO1 is considered to regulate bone homeostasis through osteoblast–osteoclast crosstalk and plays an important role in bone remodeling, osteoporosis, osteopenia, and spontaneous fractures." (PMID 35563641, 2022). "From the qRT-PCR results of Piezo1-upregulated chondrocytes in this project, Mt1 was also remarkably upregulated, which shows a consistent function in osteoporosis and osteosclerosis." (PMID 35563641, 2022). "Mice with Piezo1 deletion in chondrocytes are found to exhibit early-onset osteoporosis with multiple fractures." (PMID 34208464, 2021). "Osteoblast-specific Piezo1 knockout mice show severe osteoporosis and have less response to biophysical stimulation of bone formation." (PMID 34502380, 2021). "Of ion channels, Piezo1 and Piezo2 are hot topics of mechanosensitive molecules indispensable in skeletal tissue integrity and osteoporosis development." (PMID 34573026, 2021). "Toward this goal, we systematically examined the role of Piezo1 in bone formation using Ocn-Cre-dependent Piezo1 knockout mice, mechanical-unloading-induced mouse and cellular models, and human osteoporosis samples." (PMID 31290742, 2019). "The close relationship between PIEZO1 expression and function in osteoblasts and bone formation prompted us to explore the pathological role of Piezo1 in human osteoporosis." (PMID 31290742, 2019). "However, osteoporosis emerges as an unintended consequence of systemic PIEZO1 inhibition, likely attributable to its essential role in osteogenic differentiation." (PMID 40714837, 2025). "This suggests that Piezo1 is a key regulatory factor in bone remodeling, playing an important role not only in bone formation but also in the pathogenesis of clinical diseases such as osteoporosis and bone fracture healing." (PMID 41195420, 2025). "Targeting Piezo1 function and modulating osteoclast activity could provide a new strategy for treating osteoporosis." (PMID 41195420, 2025). "In pathological conditions such as osteoporosis, Piezo1 dysfunction may lead to excessive osteoclast activity, accelerating bone loss and the progression of osteoporosis." (PMID 41195420, 2025). "Additionally, we explore the potential of targeting Piezo1 as a therapeutic approach for musculoskeletal disorders, including osteoporosis, muscle atrophy, intervertebral disc degeneration, and osteoarthritis." (PMID 38994033, 2024). "Lastly, Piezo1 activation also slightly alleviates the osteoporosis of OVX and aged mice." (PMID 37759400, 2023).
osteoporosis (continued). "Collectively, our findings revealed a novel mechanism of osteoporosis caused by simulated microgravity, regulated by Piezo1/β‐catenin/ATF4 in BMSCs, which may be a potential therapeutic target for osteoporosis, especially caused by weightlessness or disuse." (PMID 37759400, 2023). "Furthermore, another study demonstrated that patients with osteoporosis had significantly lower PIEZO1 expression accompanied with low osteoblast marker genes." (PMID 38259612, 2023). "The generally low expression of Piezo1 in patients with osteoporosis suggests that Piezo1 could be a new drug target for this disease, a key sensor for the mechanical sensitivities of osteoblasts." (PMID 36615408, 2022). "We hypothesized that PMVS intervention may attenuate osteoporosis and activate Piezo1 or Wnt signaling to promote osteoblast function." (PMID 34502380, 2021). "Overall, our results suggest that osteoblasts, osteocytes, or both, sense and respond to changes in mechanical signals in part via activation of the Piezo1 calcium channel and identify activation of Piezo1 signaling as a potential therapeutic approach for osteoporosis." (PMID 31588901, 2019). "Interestingly, the mRNA and protein expression levels of Piezo1 in osteoporosis patients (T ≤ −2.5) were significantly lower than those in control patients (T > −2.5)." (PMID 31290742, 2019). "Furthermore, osteoporosis patients show reduced expression of Piezo1, which is closely correlated with osteoblast dysfunction." (PMID 31290742, 2019). "Nevertheless, we have demonstrated that Piezo1 plays a critical role in controlling the formation and mechanical-loading-dependent remodeling of the bone in mouse models and it is closely related with the occurrence of osteoporosis in human patients." (PMID 31290742, 2019). "Our finding that activation of Piezo1 mimics the effects of mechanical stimulation on bone cells and increases bone mass in mice sets the stage for exploration of this pathway as a therapeutic target for osteoporosis." (PMID 31588901, 2019). "Therefore, Piezo1 is gradually being considered a new target for osteoporosis intervention and may promote the development of personalized osteoporosis treatments in the future." (PMID 41195420, 2025). "However, whether intervening in the action of Piezo1 can rescue disuse osteoporosis remains unresolved." (PMID 37759400, 2023). "Piezo1/2 double knockout does not change the trabecular bone loss in botulinum toxin A induces skeletal muscle dystrophy as an in vivo model of unloading-induced osteoporosis." (PMID 34573026, 2021). "In particular, Piezo1, PC1, and PC2 are innovative therapeutic targets for osteoporosis, and their activators may be able to treat osteoporosis." (PMID 36568096, 2022). "Our results define a mechanism where Piezo1 integrates mechanical signals into the AMPK/SIRT1/PGC-1α signaling cascade to regulate mechanoadaptive bone formation, highlighting Piezo1 activation as a potential mechanism-based therapeutic strategy for disuse osteoporosis." (PMID 41362723, 2026).
osteoarthritis (26 papers, 2018 to 2026). A noninflammatory degenerative joint disease occurring chiefly in older persons, characterized by degeneration of the articular cartilage, hypertrophy of bone at the margins and changes in the synovial membrane. "The findings shed light on a partial mechanistic role of Piezo1 in chondrocyte apoptosis and offer insights for further exploration into the pathogenesis and treatment strategies of osteoarthritis." (PMID 38842129, 2024). "Among these channels, Piezo1 has been identified as a mediator of chondrocyte catabolic responses and is markedly increased in osteoarthritis." (PMID 38842129, 2024). "Consistently, chondrocytes in osteoarthritis cartilage displayed an increase in PIEZO1 expression upon IL-1α stimulation." (PMID 38627713, 2024). "Here we addressed the question if and how chondrocyte expression of the mechanosensitive proteins Piezo1 or Piezo2 controls physiological endochondral ossification and pathological osteoarthritis (OA) development." (PMID 38395992, 2024). "In osteoarthritis (OA), upregulation of chondrocyte Piezo1 expression under high strain mechanical stress consistently enhances Ca2+ signaling leading to apoptosis." (PMID 35154133, 2022). "For instance, during the development of OA (Osteoarthritis), chondrocytes secrete IL-1α, which enhances the sensitivity of PIEZO1 mechanical transduction and makes chondrocytes more vulnerable to mechanical damage via feedforward mechanisms." (PMID 35563641, 2022). "Apoptosis of chondrocyte is involved in osteoarthritis (OA) pathogenesis, and mechanical stress plays a key role in this process by activation of Piezo1." (PMID 34454425, 2021). "The mechanosensitive PIEZO1 ion channel plays a pivotal role in the regulation of chondrocyte function and is involved in various physiological and pathological processes, including cartilage degradation and osteoarthritis (OA)." (PMID 40765556, 2025). "Here, we present evidence that Piezo1 senses the mechanical stimuli to coordinate the crosstalk between mesenchymal stem cells (MSCs) and T helper 17 (Th17) cells, leading to the deterioration of bone and cartilage in osteoarthritis (OA)." (PMID 40169556, 2025). "In view of its key effect, it is very important to explore the role of Piezo1 in osteoarthritis." (PMID 40169556, 2025). "In osteoarthritis, Piezo1 induces cartilage apoptosis and inflammation, inflammatory exudation leads to increased intra-articular interstitial fluid and increased intra-articular pressure, and the increased pressure initiates apoptotic and inflammatory programs." (PMID 35154133, 2022). "Piezo1 is involved in the late apoptosis of chondrocytes in patients with osteoarthritis." (PMID 33575334, 2021). "In addition, it has been shown that PIEZO1 activation by cell stretch induces the apoptosis of human chondrocytes in osteoarthritis." (PMID 29757938, 2018). "Therefore, Piezo1-siRNA may protect the cartilage of patients with osteoarthritis, which provides a potential method for the treatment of persistent progression of OA under abnormal mechanical stimulation." (PMID 33204718, 2020). "Notably, the therapeutical effect of the non-specific inhibitor of PIEZO1, Gsmtx4, has been reported to ameliorate osteoarthritis in the animal model." (PMID 38627713, 2024). "However, whether it can be affected by Piezo1 is still not clear yet, indicating a promising direction when performing osteoarthritis research." (PMID 35563641, 2022).
glioblastoma (25 papers, 2020 to 2025). The most malignant astrocytic tumor (WHO grade IV). "Tumor models, such as glioblastoma, show that PIEZO1 overexpression enhances cellular invasion and immunosuppressive signaling via YAP/TAZ activation and MAPK-mediated cytokine release." (PMID 40863236, 2025). "For instance, Piezo1 inhibitors have been validated in liver cancer and glioblastoma models for their ability to enhance anti-tumor immune effects." (PMID 41282026, 2025). "Specific mechanistic studies centered on Piezo1 will contribute to our understanding of the mechanistic biology of glioblastoma and help us develop new therapeutic approaches for glioblastoma patients." (PMID 40061015, 2025). "Taken together, these data suggest that Piezo1 not only delivers mechanical inputs to promote glioblastoma growth but also positively regulates the ECM and other mechanotransduction mechanisms in tumors." (PMID 40061015, 2025). "As a therapeutic target for glioblastomas, Piezo1 senses microenvironmental stiffness and converts mechanical stimuli into electrical and chemical signals that promote calcium influx." (PMID 40061015, 2025). "Piezo1 regulates glioblastoma angiogenesis by engaging the Ca2+-dependent proteins eNOS and calpain, which promote the migration, alignment, and rearrangement of vascular endothelial cells in the direction of blood flow." (PMID 40061015, 2025). "Kaplan-Meier survival analysis of multiple human glioblastoma datasets showed that patients with elevated Piezo1 expression had significantly worse overall survival." (PMID 40061015, 2025). "Next, we performed differential gene expression analysis and determined that upon PIEZO1 knockout, glioblastoma cells dramatically increase expression of several stress and apoptosis-related genes including CASP8, UBB and GSN." (PMID 40791371, 2025). "In human glioblastoma cells, Piezo1 is the main component of MSCs activated by cell swelling in glioblastoma cells, and is also primarily responsible for mechanotransduction during glioblastoma cell volume regulation." (PMID 40061015, 2025). "Multifactorial Cox regression analysis showed that Piezo1 overexpression was an independent prognostic factor for overall survival (OS) in glioblastoma patients." (PMID 40061015, 2025). "Specific mechanistic studies focusing on Piezo1 will help us understand the mechanobiology of glioblastoma and help us develop new therapeutic approaches for glioblastoma patients." (PMID 40061015, 2025). "Glioblastoma, one of the most common and malignant brain tumors in adults, exhibits Piezo1 overexpression." (PMID 40061015, 2025). "In the glioblastoma tumor microenvironment, Piezo1 plays a particularly strong role in the ECM signaling pathway." (PMID 40061015, 2025). "Studies have shown that Piezo1 is largely unexpressed in normal brain tissue, but is expressed at high levels within glioblastomas." (PMID 40061015, 2025). "The cascade mechanism of Piezo1 activation from Ca2+ influx to IK/BK channel activation, which ultimately regulates cell volume, is an important signaling pathway for Piezo1 regulation of glioblastoma cell spreading, migration, and death." (PMID 40061015, 2025). "Consistent with previous reports in prostate cancer, osteosarcoma, and glioblastoma, our findings collectively demonstrate that mechanical signaling promotes malignant tumor progression via PIEZO1." (PMID 41533929, 2025). "In glioblastoma, exosomal circZNF800 from glioma stem-like cells promotes tumorigenesis by activating the PIEZO1/Akt pathway via miR-139-5p sponging." (PMID 40806720, 2025). "More recently we reported that Piezo1 controls the RVD in glioblastoma cells via the modulation of Ca2+-activated K+ channels." (PMID 38581527, 2024). "Overexpression of Piezo1 in human glioblastoma also correlates with the malignancy of the tumor and the severity of the peritumoral brain edema." (PMID 38612801, 2024).
glioblastoma (continued). "Piezo1 recruitment to focal adhesions was also shown to play a role in enhancing glioblastoma aggression by activating integrin-FAK signaling upstream of ECM remodeling and tissue stiffening." (PMID 38393325, 2024). "On the contrary, in glioblastoma, it has been reported that Piezo1 expression is upregulated in highly migratory tumor cells and that Piezo1 knockdown inhibits tumor cell migration." (PMID 37305437, 2023). "It has been postulated that vasogenic edema can be mediated through Ca2+ influx by opening the PIEZO1 ion channels, and then activating calpain and degrading the tight-junction protein between adjacent cells in glioblastomas." (PMID 36765838, 2023). "Consistent with this view, a recent observation has shown that the activity of Piezo1 channels correlated with the severity of brain edema in glioblastomas and that up-regulation of the expression of Piezo1 channels correlated to the size of brain edema." (PMID 36293444, 2022). "PIEZO1 specifically in glioblastoma serves as an intermediary for a variety of downstream affects including cytoskeletal remodeling, ECM remodeling as well as directly regulating stemness and aggression of cancer cells." (PMID 35127517, 2021). "In addition, Piezo1 expression transduces mechanical stimuli between glioblastoma cells, promoting tumorigenesis and progression." (PMID 40061015, 2025). "In glioblastoma (GBM), high Piezo1 expression is associated with poor prognosis." (PMID 40821847, 2025). "In the context of glioblastoma and CNS tumors, PIEZO1 is often overexpressed." (PMID 40863236, 2025). "Piezo1 acts as a mechanosignal receptor, transmits extracellular matrix stiffness signals, and promotes glioblastoma cell proliferation, invasion, and epithelial-mesenchymal transition by regulating the nuclear expression and activity of YAP and subsequent TAZ activation." (PMID 40061015, 2025). "Our study identified that circZNF800 and miR-139-5p are upstream of PIEZO1, which might provide genetic targets for the treatment of glioblastoma." (PMID 38324181, 2024). "Furthermore, our data are supported with another previous finding that in human glioblastoma cells, Yoda1 activates both IKCa and BKCa currents, which shows that these channels are under the control of Piezo1." (PMID 38955832, 2024). "Moreover, the overexpression of PIEZO1 contributes to more severe clinical symptoms, as was found via a retrospective analysis of imaging data and surgical samples from 64 patients with glioblastoma." (PMID 36765838, 2023). "Furthermore, Piezo1 overexpression in glioblastoma is correlated with the degree of peritumoral brain edema, a glioblastoma-associated condition that aggravates the patient’s symptoms." (PMID 37762011, 2023). "For example, glioblastoma cells sense matrix stiffness via Piezo1-mediated mechanotransduction." (PMID 35510498, 2022). "With regard to histopathologic classification, glioblastoma had the highest expression of PIEZO1." (PMID 32999349, 2020). "Studies have shown that Piezo1 is largely unexpressed in normal brain tissues but is expressed at high levels in glioblastoma and can significantly contribute to glioblastoma development and progression, but its role in the pathogenesis of glioblastoma remains unclear." (PMID 40061015, 2025). "Piezo1 is highly expressed and co-localized in extensively angiogenic GBM endothelial cells and promotes aberrant angiogenesis in glioblastoma through the HIF-1α/VEGF pathway." (PMID 40061015, 2025). "Thus, inhibition of Piezo1 reduces clinical symptoms in glioblastoma patients and may be a therapeutic target for diseases involving blood-brain barrier collapse." (PMID 40061015, 2025). "Furthermore, PIEZO1 knockdown could inhibit the growth of glioblastoma stem cells, suppress tumor progression, and prolong survival in mice." (PMID 38494915, 2024). "Enhanced stiffness between glioblastoma cells and the ECM microenvironment in turn regulates the activation of Piezo1." (PMID 40061015, 2025).